GTF2E2 (general transcription factor IIE subunit 2)
Description:
Recruits TFIIH to the initiation complex and stimulates the RNA polymerase II C-terminal domain kinase and DNA-dependent ATPase activities of TFIIH. Both TFIIH and TFIIE are required for promoter clearance by RNA polymerase.
Synonyms: TF2E2; TFIIE-B; FE; TTD6
Tractability: Small molecule: a structure with a bound ligand is known. PROTAC: ubiquitination databases record sites on it; its protein half-life has been measured.
Gene: Protein-coding gene on chromosome 8 (30,578,318 to 30,660,846, reverse strand). Ensembl gene ENSG00000197265.
Subcellular location: Nucleus
Subcellular location (Human Protein Atlas): Nucleoplasm; Cytosol
Pathways (Reactome):
Gene expression (Transcription): RNA Polymerase II Pre-transcription Events; RNA Polymerase II Promoter Escape; RNA Polymerase II Transcription Initiation; RNA Polymerase II Transcription Initiation And Promoter Clearance; RNA Polymerase II Transcription Pre-Initiation And Promoter Opening; RNA polymerase II transcribes snRNA genes
Disease: HIV Transcription Initiation; RNA Polymerase II HIV Promoter Escape; Transcription of the HIV genome
Gene Ontology:
Molecular function: protein binding; RNA binding; RNA polymerase II general transcription initiation factor activity; TFIIH-class transcription factor complex binding
Biological process: RNA polymerase II preinitiation complex assembly; transcription by RNA polymerase II; transcription initiation at RNA polymerase II promoter
Cellular component: cytosol; nucleoplasm; nucleus; transcription factor TFIID complex; transcription factor TFIIE complex
Genetic constraint (gnomAD): Loss-of-function variants: 2 observed, 5.67 expected, observed/expected ratio (o/e) 0.35, 90% interval 0.14 to 1.11. That is too few expected variants to judge how well the gene tolerates losing a copy. Missense variants: 41 observed, 45.36 expected, observed/expected ratio (o/e) 0.9, 90% interval 0.7 to 1.17. Synonymous variants: 18 observed, 19.9 expected, observed/expected ratio (o/e) 0.9, 90% interval 0.62 to 1.34.
Homologues: Orthologues: chimpanzee GTF2E2 (100% identical), macaque GTF2E2 (99% identical), dog GTF2E2 (96% identical), pig GTF2E2 (95% identical), mouse Gtf2e2 (94% identical), rat Gtf2e2 (94% identical), tropical clawed frog gtf2e2 (82% identical), rabbit GTF2E2 (80% identical), zebrafish gtf2e2 (79% identical), Drosophila melanogaster TfIIEbeta (55% identical), Caenorhabditis elegans gtf-2E2 (40% identical).